MUC1 (mucin 1, cell surface associated)
Diseases named in the same sentence as MUC1 in open-access papers (continued):
Sharing a sentence is not in itself a finding about the gene and the disease.
lymph node metastasis (40 papers, 2004 to 2025). "High MUC1 expression in lymph node metastases was associated with the presence of distant metastasis and adverse prognosis." (PMID 41332218, 2025). "The positive expression of MUC1 was associated with aggressive pathologic features of GC including diffuse-type cancer, advanced cancer, lymph node metastasis, and distant metastasis." (PMID 36831343, 2023). "A higher MUC1 combined score was significantly associated with male gender (p = 0.03), lymph node metastasis (p < 0.01), lymphovascular invasion (p = 0.045), and extracapsular extension (p = 0.03)." (PMID 35389164, 2022). "High MUC1 expression was significantly associated with low histological grade and lymph node metastasis." (PMID 33060563, 2020). "Statistical significance was reached that MUC1 overexpression, as detected by immunohistochemistry, was significantly associated with vascular invasion, lymph node metastasis, and 5-year survival." (PMID 27190429, 2016). "Additionally, high MUC1 expression was associated with a higher stage (RR 1.44), depth of invasion (RR 1.30), and lymph node metastasis (RR 1.47)." (PMID 36900282, 2023). "The present data shows that in our cohort male gender (p = 0.03), the presence of lymph node metastasis (p < 0.01), lymphovascular invasion (p = 0.045), and extracapsular extension (p = 0.03) were significantly associated with a higher mean MUC1 combined score among all SGC." (PMID 35389164, 2022). "However, several studies have also shown aberrant expression of MUC1 in GC, which could be associated with deeper invasion and lymph node metastasis." (PMID 35328248, 2022). "MUC1(+) tumors are more likely to have lymph node metastasis and cleaved caspase-3 expression, as well as a larger tumor diameter than those that are MUC1(-)." (PMID 40655139, 2025). "While MUC1 expression is ubiquitous, MUC5AC expression has emerged as a significant prognostic factor associated with lymph node metastasis and poor OS." (PMID 38893239, 2024). "Depolarized MUC1 expression and its relationship with poor prognostic parameters such as lymph node metastasis and stage have been well documented among lung adenocarcinomas." (PMID 36367122, 2023). "Patients with MUC1 expression had a higher rate of deeper tumor depth (T staging), lymph node metastasis (N staging), and distant metastasis (M staging)." (PMID 36831343, 2023). "We found that tumor size (p=0.006), lymphatic invasion (p=0.018), vascular invasion (p=0.025), perineural invasion (p=0.019), mean MUC1 IRS score (p=0.018), and MUC1 IRS scores >8.5 (p=0.018) were significant predictors for lymph node metastasis." (PMID 36367122, 2023). "We showed that MUC1 FIRS scores were higher in patients with lymph node metastasis, and tumors with a FIRS score of >8.5 were 2.75 times more likely to metastasize." (PMID 36367122, 2023). "Tumor size (p=0.006), lymphatic invasion (p=0.018), vascular invasion (p=0.025), perineural invasion (p=0.019), MUC1 IRS scores (p=0.018), and MUC1 IRS scores >8.5 (p=0.018) were significant predictors for lymph node metastasis." (PMID 36367122, 2023). "Similar to the results of our study, MUC1 positivity had a higher rate of vascular invasion (odds ratio [OR] 1.64, 95% CI 1.13–2.39) and lymph node metastasis (OR 2.10, 95% CI 1.20–3.67) in this meta-analysis." (PMID 36831343, 2023). "For lymph node metastasis, higher MUC1 expression was related to poor prognosis (n = 11, RR = 1.40, 95% CI: 1.14-1.72, p = 0.002), but MUC4 was not (n = 2, RR = 1.23, 95% CI: 0.82-1.83, p = 0.317)." (PMID 29221212, 2017). "We observed a correlation of MUC1 positivity with higher rate of vascular invasion and lymph node metastasis." (PMID 27190429, 2016). "Here we also confirmed that overexpression of MUC1 correlated with lymph node metastasis and recurrence in ESCC patients." (PMID 26667143, 2015). "Overexpression of MUC1 has been observed in many types of adenocarcinoma and correlated with lymph node metastasis and poor prognosis in patients." (PMID 25675408, 2015).
lymph node metastasis (continued). "Relationship between expression of MUC4 and MUC1 and lymphatic invasion (ly), venous invasion (v) or lymph node metastasis (N)." (PMID 23152882, 2012). "MUC1 is of special interest as upregulation is significantly correlated to the depth of invasion, lymph node metastasis, and peritoneal dissemination." (PMID 24212784, 2011). "MUC1 upregulation was significantly correlated to the depth of invasion, lymph node metastasis and peritoneal dissemination." (PMID 15599383, 2004). "Additionally, the difference in MUC1 expression between the primary tumor and lymph node metastasis was related to metastatic status and survival, with a reduction in expression in nodal metastasis in cases without distant metastasis and better prognosis." (PMID 41332218, 2025). "In contrast, other mucins such as MUC1 and MUC21 have been reported in LUAD and NSCLC, with roles in immune modulation and EGFR mutation-specific expression patterns, but their associations with lymph node metastasis remain less clearly defined." (PMID 41409294, 2025). "However, MUC6 expression within CRC is lower (up to 39%) compared to other mucins such as MUC1, which is expressed in 84% of patients with lymph node metastases." (PMID 36900282, 2023). "Overexpression of MUC1 and MUC3 was reported in 90% of BC cases and found to be associated with high local recurrence and lymph node metastasis, suggesting the application of a MUC1-MUC3 detection panel for the prediction of local recurrence and lymph node metastasis." (PMID 36980526, 2023). "In early GC, patients with a high level of MUC1 expression showed a higher rate of lymphovascular invasion, which is a strong risk factor for lymph node metastasis and noncurative resection after endoscopic submucosal dissection." (PMID 36831343, 2023). "MUC1 FIRS scores may be used as a predictor for lymph node metastasis in addition to conventional parameters such as lymphovascular and perineural invasion." (PMID 36367122, 2023). "In conclusion, findings from the current study suggest that MUC1 and MUC2 expression levels in CRC tissues are associated with OS, DFS/RFS, tumor site, depth of invasion, lymph node metastasis, distant metastasis, tumor stage, histologic type, and lymphatic invasion." (PMID 31933627, 2019). "In addition, expression of MUC1 proved to be a marker of tumor progression and lymph node metastasis." (PMID 27298226, 2016). "In the low MUC1 group (n = 11), larger tumors, higher nuclear grade, lymph node metastasis, and negativity for estrogen receptor was more frequently identified compared to the high MUC1 group (n = 11; p = 0.01, p = 0.002, p = 0.008, and p = 0.02, respectively)." (PMID 27846863, 2016). "The expressions of CCR7 and MUC1 were both positively correlated with lymph node metastasis." (PMID 26667143, 2015). "The co-expression of CCR7 and MUC1 was also positively correlated with lymph node metastasis." (PMID 26667143, 2015). "Although MUC1 expression is universal, MUC5AC expression is a significant prognostic indicator that correlates with lymph node metastasis and poor OS." (PMID 38893239, 2024). "In 89 patients with lymph node metastasis, there were 60 (67.4 %) patients with positive CCR7 expression, and 67 (75.3 %) patients with positive MUC1 expression." (PMID 26667143, 2015). "Despite these findings, our study did not reveal significant associations between MUC1 or MUC5AC expression and histopathological features such as lymph node metastasis, LVI, PNI, TILs, or necrosis." (PMID 40821195, 2025). "In our case, in spite of MUC1-positive staining and submucosal invasion, no lymph node metastasis was detected." (PMID 23251182, 2012). "In summary, the present study introduces an alternative scoring for MUC1 that may serve as a predictor for lymph node metastasis regardless of the histologic subtype." (PMID 36367122, 2023).
lymph node metastasis (continued). "The rates of submucosal invasion (85.7% vs. 42.9%, p = 0.061) and lymph node metastasis (28.6% vs. 7.1%, p = 0.186) were higher in patients with a high level of MUC1 expression than in those without MUC1 expression, although there was no statistical significance." (PMID 36831343, 2023). "We did not examine the immunostaining of MUC-1; however, there may be a relationship between extensive lymph node metastasis and VEGF-C and MUC-1." (PMID 24708742, 2014). "In 64 patients without lymph node metastasis, there were 29 (45.3 %) patients with positive CCR7 expression and 22 (34.4 %) patients with positive MUC1 expression." (PMID 26667143, 2015). "Meanwhile, in the 89 patients with lymph node metastasis, 53 patients co-expressed CCR7 and MUC1 (59.6 %), seven patients only expressed CCR7 (13.2 %), 18 patients only expressed MUC1 (20.2 %), and 11 patients did not express CCR8 or MUC1 (12.4 %)." (PMID 26667143, 2015). "None of the expression of MUC1, MUC2, and MUC4 was significantly related to gender, age, differentiation, lymph node metastasis, or depth of invasion." (PMID 23101681, 2012). "To further assess whether the MUC1 and/or MUC4 methylation status affect prognosis, we divided patients into two groups based on the presence or absence of lymph node metastasis." (PMID 27283771, 2016).
triple-negative breast carcinoma (40 papers, 2014 to 2026). An invasive breast carcinoma which is negative for expression of estrogen receptor (ER), progesterone receptor (PR), and human epidermal growth factor receptor 2 (HER2). "Mucin1 (MUC1), a glycoprotein associated with chemoresistance and an aggressive cancer phenotype, is aberrantly overexpressed in triple-negative breast cancer (TNBC)." (PMID 28464016, 2017). "MUC1 is notably overexpressed in early basal-like triple-negative breast cancer, which provides a theoretical basis for MUC1-based immunotherapy." (PMID 41409286, 2025). "Maeda and coworkers indicated that transcription of PD-L1 was increased by MUC1 by activating NF-κB and Myc in triple-negative breast cancer." (PMID 38418707, 2024). "CAR T cells were activated using CD3+CD28-coated beads or co-culture with (MUC1+ ErbB+) MDA-MB-468 triple-negative breast cancer (TNBC) cells, making comparison with unstimulated controls." (PMID 38745414, 2024). "CAR T cells that target hypoglycosylated MUC1 have demonstrated remarkable efficacy against triple-negative breast cancer model (TNBC) and head and neck cancer." (PMID 38611013, 2024). "We found that KK-LC-1 expression was significantly positively correlated with MAL2 and MUC1 expression in 126 triple-negative breast cancer specimens." (PMID 36895039, 2023). "Supernantant containing a MUC1.BiTE enhanced unmodified T cell killing of MUC1+ triple negative breast cancer cell line SUM-159 from 16% to 75%." (PMID 35681750, 2022). "MUC1 is also aberrantly expressed in triple-negative breast cancer, where it contributes to epigenetic reprogramming, chromatin remodeling and chemoresistance." (PMID 36430448, 2022). "In the present study, the role of MUC1 expression was investigated with respect to triple-negative breast cancer (TNBC) metabolism." (PMID 28464016, 2017). "MUC1 is aberrantly overexpressed in luminal, HER2+ and basal-like triple-negative breast cancers as a result in part of MUC1 gene alterations and dysregulation of transcription." (PMID 24770886, 2014). "Furthermore, the combination of the Mucin-1 (MUC1)-mRNA DC vaccine with CTLA-4 blockade outperformed either the DC vaccine or CTLA-4 blockade alone in patients with triple-negative breast cancer (TNBC)." (PMID 39062753, 2024). "Meanwhile, MUCIN 1 (MUC1) could bind to the CD44 variant to enhance the stability of SLC7A11, thereby inhibiting erastin-induced ferroptosis in triple-negative breast cancer cells." (PMID 35795552, 2022). "Several researchers have also isolated specific antibodies against the extracellular structure of MUC1-C that recognize recombinant MUC1 and the native MUC1-C protein in breast cancer cells and screened for antibodies that highly inhibit the invasion of triple-negative breast cancers." (PMID 34207342, 2021). "Besides, a previous study from the Hasegawa group has reported that the ferroptosis inhibitor sulfasalazine, which targets SLC7A11, can increase DNA methylation on the mucin 1 gene (MUC1) promoter to regulate MUC1 gene transcription in triple-negative breast cancer." (PMID 37488128, 2023). "In addition, combination of mucin 1 (MUC1) mRNA nanovaccines with anti-CTLA-4 has also demonstrated enhanced antitumor effects against triple-negative breast cancer by improving the immunosuppressive tumor microenvironment (TME) and increasing CD8 + T cells, IFN-γ, and IL-12 levels." (PMID 37415161, 2023). "More than 90% of triple-negative breast cancers (TNBC) and 80% of pancreatic ductal adenocarcinoma (PDAC), both highly aggressive cancer types, present with the aberrantly expressed MUC1." (PMID 38611013, 2024). "To further validate the relationships between KK-LC-1, MAL2, and MUC1 expression, we detected the expression of KK-LC-1, MAL2, and MUC1 in 126 triple-negative breast cancer clinical samples." (PMID 36895039, 2023).
triple-negative breast carcinoma (continued). "In this study, anti-tumor CTL activity induced by combination of CTLA-4 Blockade with MUC1 mRNA nanovaccine and immunosuppressive factors in the TME of triple negative breast cancer were investigated." (PMID 34875483, 2022). "Further study, however, has developed CAR T cells recognizing the altered glycosylated epitope within the MUC1 tandem repeat sequence (TAB004), which also demonstrated potent and selective antitumor activities in triple-negative breast cancer." (PMID 36457849, 2022). "Overexpression of the oncoprotein Mucin 1 (MUC1) is correlated to NF-κB-mediated PD-L1 expression in both NSCLC and triple-negative breast cancer (TNBC)." (PMID 33324403, 2020). "Taken together, these data suggest that MUC1 mRNA-based vaccination, especially in combination with inhibition of the immune checkpoint CTLA-4, is a promising immunotherapeutic approach for the treatment of triple-negative breast cancer." (PMID 40943370, 2025). "A study investigating MUC1 expression in 52 cases of early-stage triple-negative breast cancer (TNBC) found that 94% of the cases were MUC1-positive, with 67% exhibiting moderate to strong MUC1 expression, 27% demonstrating weak MUC1 expression, and 6% lacking MUC1 expression." (PMID 41471303, 2025). "In addition, the anti-MUC1 aptamer was labeled with 99mTc to generate a labeled drug delivery system (DDS), which was subsequently used for in vivo imaging of triple-negative breast cancer (TNBC)." (PMID 37894512, 2023).
lung adenocarcinoma (39 papers, 2007 to 2026). A carcinoma that arises from the lung and is characterized by the presence of malignant glandular epithelial cells. "The MAPS signature, comprised of MUC1-CD-dependent genes involved in the control of cell cycle and proliferation, is associated with poor outcomes in patients with adenocarcinoma of the lung." (PMID 20459602, 2010). "MUC1 overexpression is associated with poor prognosis in breast and lung adenocarcinoma; however, its influence in the prognosis of mesothelioma has not been reported." (PMID 18454162, 2008). "The modification of CAR-T cells targeting the lung adenocarcinoma antigen MUC1 for the chemokine receptor CCR6 enhanced migration toward tumor sites rich in CCL20 and CAR-T cell efficacy." (PMID 41181132, 2025). "Patients with squamous carcinoma and lung adenocarcinoma had higher percentages of elevated MUC1 expression (86.3 and 39.1%, respectively) in prior research involving 178 patients with stage IB NSCLC." (PMID 38540735, 2024). "In our A549 model, MUC-1 was markedly overexpressed with depolarized expression pattern, reminiscent of in vivo lung adenocarcinoma." (PMID 37434755, 2023). "In cancer patients, MUC1 gene expression is significantly higher in lung adenocarcinoma than in normal lung tissues (p = 2.52e-02)." (PMID 36810913, 2023). "Clinically, higher expression of MUC1 correlates with less overall and disease-free survival in lung adenocarcinoma patients at advanced stages." (PMID 36810913, 2023). "MUC1 affects cancer progression in lung adenocarcinoma, and its aberrant expression pattern has been correlated with poor tumor differentiation and impaired prognosis." (PMID 35205621, 2022). "Then we detected the expression of YBX1 and MUC1 in the cancer tissues and adjacent tissues of 6 lung adenocarcinoma patients, and we observed significantly high expression of both in the tumors." (PMID 34976785, 2021). "Our retrospective cohort study of 176 lung adenocarcinoma patients after surgery showed that low expression of both YBX1 and MUC1 was an independent predictor of the prognosis and recurrence of lung adenocarcinoma." (PMID 34976785, 2021). "In lung adenocarcinoma cells, the silencing/overexpression of YBX1 caused a simultaneous change in MUC1, and MUC1 overexpression partially reversed the decreased tumor cell migration, aggressiveness, and stemness caused by YBX1 silencing." (PMID 34976785, 2021). "Similar to existing research, YBX1 or MUC1, as separate tumor markers, can predict prognosis in lung adenocarcinoma patients." (PMID 34976785, 2021). "It is a type of MUC1 mucin recognised by a monoclonal antibody derived from mice immunised with a human lung adenocarcinoma cell line." (PMID 34088359, 2021). "In conclusion, the low coexpression of YBX1/MUC1 showed vital prognostic significance in the prognosis and recurrence of lung adenocarcinoma." (PMID 34976785, 2021). "Our data were in agreement that in the presence of TAMs, NF-κB and MUC1 expression were increased in both A549 and H441 lung adenocarcinoma cell lines." (PMID 27276704, 2016). "On the other hand, it is interesting to note that MUC1 in combination with other proteins have been proposed as immunohistochemical tests for subclassification of lung adenocarcinoma and SCC." (PMID 24625834, 2014). "In contrast, lung adenocarcinomas, especially well-differentiated cancers, exhibited increased MUC1 and MUC3 mRNA levels." (PMID 17349047, 2007). "The purpose of this work was to investigate whether ectopic expression of MAL could modify the proliferative activity of MUC1 in human lung adenocarcinoma HCC827 cells." (PMID 42038033, 2026). "Higher expression of the MUC-1 antigen in NSCLC may be related to the fact that it is a marker of lung adenocarcinoma, which is supported by histopathological studies." (PMID 39941799, 2025).